ACTA2 (actin alpha 2, smooth muscle)
Diseases named in the same sentence as ACTA2 in open-access papers (continued):
Sharing a sentence is not in itself a finding about the gene and the disease.
liver fibrosis (continued). "Consistently, the upregulation of hydroxyproline, serum ALT and AST levels, and hepatic protein level of α-SMA and mRNA levels of Col1α1, Acta2 and TIMP-1 were also increased in IFN-γ-/- Vγ4 cells reconstituted mice, while IL-17-/- γδ T cells still showed protection against hepatic fibrosis." (PMID 35361750, 2022). "Furthermore, levels of liver transcripts of genes indicative of liver fibrosis, such as transforming growth factor beta 1 (TGFB1), actin alpha 2 (Acta2) (αSMA) and collagen type I alpha 1 (Col1a1), were measured." (PMID 35057565, 2022). "Furthermore, it was observed that the levels of Acta2, Col1a1, Col3a1, Tnfa, Il6, and Il1β genes were significantly increased upon STAT3 overexpression, again suggesting that STAT3 mitigated liver fibrosis." (PMID 36588728, 2022). "We therefore examined liver fibrosis markers in both the CBDL and CCl4 models of liver injury and in both cases found a more severe damage and fibrosis with increased TIMP-2, Collagen-1, and ACTA-2 gene expressions." (PMID 33391458, 2021). "In addition, rottlerin treatment also suppressed TGFβ1-induced expression of ACTA2, COL1A1, COL1A2, and CCL2, the expression of which is greatly increased in HSCs of liver fibrosis patients." (PMID 32210801, 2020). "Additionally, expression of pro-fibrotic genes, including Acta2, Col1a1, and Tgfb1 was significantly higher the CDAA and CDAA + fructose groups in parallel with the differences in liver fibrosis and numbers of activated HSCs." (PMID 29983886, 2018). "Nicotine administration did not affect hepatic fibrosis, Acta2 expression at the mRNA level, or number of α-SMA-positive cells in CSAA-diet-fed rats." (PMID 28662136, 2017). "Similarly as in the CCl4 model, we have not observed differences in the degree of liver fibrosis, hydroxyproline content, aminotransferase activities and Col1a1/Acta2 between Cre+ and Cre-mice in the DDC model." (PMID 39529885, 2024). "As expected from previous publications, WT (i.e., Ccne1f/f) mice developed pronounced liver fibrosis with excessive hepatic collagen deposition upon combined DEN/CCl4 treatment, which was accompanied by substantial induction of Col1a1 gene expression and upregulation of Acta2." (PMID 37620309, 2023). "However, nicotine administration significantly attenuated hepatic fibrosis and Acta2 expression at the mRNA level, but not the number of α-SMA-positive cells in CDAA-diet-fed rats." (PMID 28662136, 2017). "Indeed, nizatidine significantly reduced liver fibrosis measured by collagen proportionate area (CPA), α smooth muscle actin (αSMA) staining, quantitative analysis of hydroxyproline, and expression of genes mediating fibrogenesis (Acta2, Col1a1, Tgfb-1, and Timp1)." (PMID 34535664, 2021). "Acta2 was increased in BDL rat livers compared to sham, and this was not reduced or altered by treatment with IFX, indicating that short-term IFX treatment does not reduce liver fibrosis." (PMID 29263339, 2017).
lung fibrosis (36 papers, 2017 to 2025). "In addition to the upregulation of typical fibrosis-associated genes (Col1a1, Fn1 and Acta2), an increase in Prrx1a and Prrx1b mRNA expression was previously reported during fibrosis development in the bleomycin model of lung fibrosis." (PMID 40856011, 2025). "However, a significant increase in Acta2 expression (encodes for α-smooth muscle actin, a mesenchymal marker) was revealed in Plaur-/- mice on Day 14 and Day 21 of bleomycin-induced pulmonary fibrosis (2-way ANOVA, Holm–Šídák’s test, p < 0.05)." (PMID 36674896, 2023). "Interleukin-11 (IL-11) is a profibrotic cytokine essential for the differentiation of fibroblasts into collagen-secreting, actin alpha 2, smooth muscle–positive (ACTA2+) myofibroblasts, driving processes underlying the pathogenesis of idiopathic pulmonary fibrosis (IPF)." (PMID 35731866, 2022). "At 21 d.p.i., deletion of both Yap and Taz in myofibroblasts strongly attenuated lung fibrosis and suppressed the expression of key myofibroblast activation and profibrotic genes, including Acta2, Col1a1, Postn, Fn1, Col3a1, and Tgfb1." (PMID 40454481, 2025). "Our study shows that inhibition of NF-κB in the lungs significantly reduced Acta2 expression in BLM treated IKBM mice indicating an effective therapeutic approach for the treatment of pulmonary fibrosis." (PMID 35083615, 2022). "HuR appears to function via direct binding to mRNAs for COL1A1, COL3A1, ACTA2, and FN, and it was found that HuR is localized to a greater degree in the cytosol in cells from mouse lung fibrosis models as well as human idiopathic pulmonary fibrosis patients." (PMID 35892569, 2022). "Similar to the results in lung fibrosis, expression of Col1a1, Col1a2, and Acta2 was inhibited in MHP1-AcN-treated mice." (PMID 35864207, 2022). "In the pseudostratified monocultures of the HBECs we observed the TGF-β1–induced EMT program described in lung fibrosis leading to the enhancement of the expression of mesenchymal genes as ACTA2, CDH2 and EMT-related transcription factors SNAI1 and SNAIL2." (PMID 33711932, 2021). "During lung fibrosis, the expression of Acta2 and collagen 1a1 (Col1a1) and 3a1 (Col3a1) in the PDGFR-β+ cell lineage is markedly increased." (PMID 34893592, 2021). "Using a binary lineage-tracing approach (Acta2-tdT and Pdgfra-tdT) in two distinct animal models of lung fibrosis (bleomycin and Fra-2 Tg), we show anatomically preferential localization of αSMA- and PDGFRα-expressing cells at baseline and in fibrosis." (PMID 32023084, 2020). "The lung fibrosis was examined by Masson’s trichrome (MT) stain of paraffin sections and mRNA expression levels of Col1a1, Col3a1, and Acta2 in different frozen lung samples." (PMID 29497425, 2018). "In this study, BLCN-induced pulmonary fibrosis was indicated after calculating the fibrosis score, immunohistochemical examination of the expression of ACTA2, the gene expression level of col1a1, hydroxyproline lung content, and the protein expression levels of TIMP-1 and PDGF-BB." (PMID 37631038, 2023). "Notably, we found that intranasal administration of PNA-33 markedly reduces lung fibrosis, as indicated by a significant decrease in collagen content and fibrogenic gene expression (Col1a1 and Acta2) compared with mice treated with scrambled control." (PMID 36626225, 2023). "Moreover, BLM-induced lung fibrosis in WT mice was significantly reduced in myeloid cell TERT-deficient mice as manifested by several markers of fibrosis, including α-SMA (Acta2), type I collagen (col1a2), and TGFβ (Tgfb)." (PMID 36045668, 2022).
lung fibrosis (continued). "In contrast, upregulating the expression of miR-497-5p could induce the expression of Acta2 and Col1a1 and contribute to the phenotype of pulmonary fibrosis by activating the Mmps/TGF-β pathway." (PMID 28098218, 2017). "miR-33M/M–/– mice were protected from bleomycin-induced lung fibrosis, as indicated by a reduction in collagen content, measured by hydroxyproline assay (fold change, –2; P ≤ 0.0001) and expression of profibrotic genes including Col1a1 and Acta2 (fold change, –2.5; P ≤ 0.0001)." (PMID 36626225, 2023). "Fibrosis-related genes include Col1a1, Acta2, Fn1, and Tgfb1 gene, and senescence-related genes composed of Cdkn2a, Tnf, Serpine1, Ccl2, Mmp10, and Mmp12 gene, all of which reflected the intensity of lung fibrosis and senescence events in lung tissue and pulmonary fibroblasts." (PMID 35662697, 2022). "Fibronectin 1 (Fn1), a key ECM component in pulmonary fibrosis, was upregulated upon TGF-β1 stimulation, along with Acta2, Col1a1, and Col3." (PMID 40867551, 2025). "R2M3-26 significantly decreased the Modified Ashcroft Score and percentage lung fibrosis, and R2M3-26 and RSPO2 treatments showed trended decreases in the Severity Score and ACTA2 levels." (PMID 38566174, 2024). "IL-11 plays an important role in idiopathic pulmonary fibrosis (IPF), which can differentiate fibroblasts into collagen-secreting, actin alpha 2 and smooth muscle-positive (ACTA2+) myofibroblasts." (PMID 39199292, 2024). "The phenomenon of endothelial-to-mesenchymal transition (EndoMT) is critical in lung fibrosis which is characterized by acquiring mesenchymal phenotype, such as α-SMA (Acta2)." (PMID 35083615, 2022). "We then examined the expression of IL-11 and ACTA2 in lung sections from IPF patients and the mouse model of bleomycin-induced pulmonary fibrosis." (PMID 35731866, 2022). "In addition, activated Smad signals stimulated subsignals, such as to levels of type I collagen (Col1), α-smooth muscle actin (Acta2/α-SMA), and fibroblast-specific protein 1 (Fsp1/S100A4), related to collagen accumulation and lung fibrosis." (PMID 37107342, 2023). "While our in vitro findings in adult Human lung fibroblasts showed that PRRX1 inhibition mainly impacted ACTA2 expression levels, Prrx1 ASO treatment in the bleomycin mouse model of lung fibrosis also inhibited the deposition of ECM proteins such as Collagen 1, Fibronectin, Tenascin C, and Elastin." (PMID 37261432, 2023). "First, a significant up-regulation of IL-11 and actin alpha 2, smooth muscle (ACTA2) in lung tissues from both IPF patients and the mouse model of bleomycin-induced pulmonary fibrosis was observed, and a strong correlation was identified by quantitative analysis of the immunohistochemistry images." (PMID 35731866, 2022). "We found that Acta2-reporter activity was comparable between BLM-treated and non-treated organoids of Tgfbr2-null AT2 cells, demonstrating that autocrine TGF-β signaling in AT2 cells plays a crucial role in fibroblast-to-myofibroblast differentiation in BLM-induced lung fibrosis." (PMID 37653024, 2023).
breast carcinoma (33 papers, 2013 to 2025). "In high‐risk breast cancer patients, relapse‐free survival was reduced when the expression levels of ACTA2, STAT1, and HER2 were increased." (PMID 34179721, 2021). "High-risk breast cancer patients with highly expressed ACTA2, STAT1, and HER2 had significantly decreased relapse-free survival." (PMID 28881584, 2017). "The study demonstrated that overexpression of HER2 led to increases in STAT1 and ACTA2 in EGFR+ breast cancer cells, whereas the use of the STAT1 inhibitor fludarabine resulted in decreased ACTA2 mRNA and HER2 protein levels." (PMID 40732340, 2025). "For example, Fibroblast Activation Protein (FAP) and Smooth Muscle Actin (alpha SMA/ACTA2) have been employed as a marker of activated CAFs in colorectal and breast cancer respectively, because of their high expression in the tumor stroma." (PMID 37626157, 2023). "In cell clusters associated with MSCs or the progeny (i.e., cancer-associated fibroblasts, CAFs) in the whole tumor data, it was evident that MSC-related cells were the major source of THY1 (CD90), CXCL12 and ACTA2 expression in breast cancer patient samples." (PMID 36940196, 2023). "Dimerization of EGFR and HER2 receptors mediates ACTA2 overexpression through the JAK2/STAT1-dependent signaling pathway to trigger motility of breast cancer cells." (PMID 35954483, 2022). "In breast cancer, while iCAFs (PDGFRB+, ACTA2-, CD34+, MCAM-) were implicated in cytotoxic T cell dysfunction of tripe-negative breast cancer, myCAFs (ecm) and myCAFs (TGFβ) were shown to be the primary resistance elements of immunotherapies." (PMID 34869001, 2021). "Based on these results, we propose that ACTA2 induction by HER2 overexpression was involved in breast cancer cell motility." (PMID 28881584, 2017). "In conclusion, we demonstrated that dimerization of EGFR and HER2 induced ACTA2 expression through a JAK2/STAT1-dependent signaling pathway that triggers breast cancer cell motility." (PMID 28881584, 2017). "Invasiveness of HER2-overexpressing MDA-MB231 and 4T1 mammary carcinoma cells was also suppressed by ACTA2 shRNA overexpression." (PMID 28881584, 2017). "We injected vec- or ACTA2 shRNA-transfected 4T1 mammary carcinoma cells into right secondary mammary fat." (PMID 28881584, 2017). "The metastatic potential of 4T1 mammary carcinoma cells xenograft tumors was suppressed by ACTA2 shRNA overexpression." (PMID 28881584, 2017). "HER2-overexpressing MDA-MB231 cells and 4T1 mammary carcinoma cells were stably transfected with vec-alone or ACTA2 shRNA." (PMID 28881584, 2017). "Taken together, these results demonstrated that dimerization of EGFR and HER2 activates the JAK2/STAT1 signaling axis and induces ACTA2 expression in breast cancer cells." (PMID 28881584, 2017). "ACTA2 mRNA expression decreased to 0.45 ± 0.03-fold (HER2-overexpressing MDA-MB231 cells) and 0.64-fold (4T1 mammary carcinoma cells) of controls with ACTA2 shRNA overexpression." (PMID 28881584, 2017). "We investigated the effect of ACTA2 on metastasis using 4T1 mammary carcinoma cells, which are highly tumorigenic and a model of invasion." (PMID 28881584, 2017). "Lung metastasis of 4T1 mammary carcinoma cells was also suppressed by ACTA2 silencing in an in vivo mouse model." (PMID 28881584, 2017). "The upregulation of ACTA2 in CAS of our canine mammary carcinoma samples is consistent with the results from human studies in which the increase of its gene product, αSMA, is associated with poor prognosis." (PMID 28531107, 2017). "We also found that motility of breast cancer cells was suppressed by ACTA2 silencing in breast cancer in in vitro and in vivo models." (PMID 28881584, 2017). "Levels of ACTA2, STAT1, and HER2 were increased and relapse free survival was decreased in high-risk breast cancer patients." (PMID 28881584, 2017). "Migration of HER2-overexpressing MDA-MB231 and 4T1 mammary carcinoma cells significantly decreased with ACTA2 shRNA overexpression." (PMID 28881584, 2017).
breast carcinoma (continued). "We investigated the effect of ACTA2 on breast cancer cell motility." (PMID 28881584, 2017). "Therefore, we propose that elevated ACTA2 expression induced the metastatic and proliferative potential of breast cancer." (PMID 28881584, 2017). "ACTA2 silencing also decreased the metastatic potential of breast cancers." (PMID 28881584, 2017). "Similarly, we chose RHOA, MKI67, CITED2, ACTA2, FN1 and TGFB3, as all have been implicated in EMT and highly metastatic breast cancer." (PMID 23441166, 2013). "Thus, the interaction between DDX3X and ACTA2 in breast cancer might be related to the same mechanism and could be further explored." (PMID 35954483, 2022). "Furthermore, elevated ACTA2 triggered the motility of breast cancer cells." (PMID 28881584, 2017). "Further subtype analysis based on established breast cancer CAF classification, showed DKK1 expression in ACTA2+COL1a1highPDGFRα+ myofibroblasts (myCAF)." (PMID 39885132, 2025). "These experiments suggest that the co-culture of primary human lung fibroblasts with breast cancer cells leads to a significant and steady increase in gene expression of SPP1, IGF1, POSTN and ACTA2." (PMID 40017592, 2025). "With respect to canonical CAF markers, one theme in breast cancer CAFs from scRNA seq data includes use of these markers to stratify populations, such as by PDPN versus FSP or Fap/Fsp/Acta2/Pdgfrb status." (PMID 38525245, 2024). "EGFR and HER2 dimerization modulated ACTA2 through the JAK2/STAT1 signaling pathway and ACTA2 gene abnormalities accelerated the invasion and metastasis of breast cancer cells." (PMID 34179721, 2021). "Co-exposure to TGF-β1 and E2 resulted in a trend of increased expression of VIM and ACTA2 compared to TGF-β1 alone which is consistent with one study that reported E2 promoted reversible EMT-like transition and collective motility in breast cancer cells." (PMID 30165855, 2018). "We found that breast cancer patients with tumors with high ACTA2 and HER2 levels had a poorer prognosis than patients with tumors with low ACTA2 and HER2 levels." (PMID 28881584, 2017). "Aberrant ACTA2 and STAT1 expression correlated with worse clinical outcomes of breast cancer patients." (PMID 28881584, 2017). "We investigated the regulatory mechanism of ACTA2 expression in EGFR-positive and/or HER2-positive breast cancer cells." (PMID 28881584, 2017). "Rates of cell invasion by ACTA2 silencing decreased to 50.59% (HER2 overexpressed MDA-MB231 cells) and 51.67% (4T1 mammary carcinoma cells) of the vec-alone cells." (PMID 28881584, 2017). "We also investigated the effect of ACTA2 on cell motility, which was suppressed by ACTA2 shRNA overexpression in MDA-MB231 HER2 and 4T1 mammary carcinoma cells." (PMID 28881584, 2017). "HER2 overexpression resulted in enhancement of ACTA2 and STAT1 expression in EGFR-positive breast cancer cells." (PMID 28881584, 2017). "We also analyzed the patterns of ACTA2 and STAT1 expression in HER2-negative and HER2-positive breast cancers from patients using the GEO database (GSE19615)." (PMID 28881584, 2017). "ACTA2 and STAT1 expression was also higher in HER2-positive breast cancers than in HER2-negative cancers." (PMID 28881584, 2017). "Based on these results, we propose that increased ACTA2 expression is important for cell invasion and migration in EGFR and HER2-positive breast cancer cell models." (PMID 28881584, 2017). "The levels of ACTA2 and STAT1 were increased in HER2-overexpressing breast cancer cells and tumors from HER2-positive breast cancer patients." (PMID 28881584, 2017). "Taken together, our results showed that at least COL1A1, ACTA2, and FAP were significantly upregulated on mRNA levels in CAS from canine mammary carcinoma similar to human mammary carcinoma samples, whereas CXCL12 is downregulated." (PMID 28531107, 2017). "By analyzing the public dataset, we found that ACTA2 and STAT1 expression were relatively higher in HER2-positive than in HER2-negative breast cancers." (PMID 28881584, 2017).